CRISPLD2 (cysteine rich secretory protein LCCL domain containing 2)
Description:
Promotes matrix assembly.
Synonyms: CRISP11; LCRISP2; DKFZP434B044; LGL1
Tractability: Antibody: its Gene Ontology location is reachable by antibodies, with high confidence; UniProt places it where antibodies can reach, with medium confidence; UniProt predicts a signal peptide or a membrane-spanning region.
Gene: Protein-coding gene on chromosome 16 (84,819,981 to 84,920,768, forward strand). Ensembl gene ENSG00000103196.
Subcellular location: Secreted
Subcellular location (Human Protein Atlas): Vesicles; Predicted to be secreted
Pathways (Reactome):
Immune System: Neutrophil degranulation
Gene Ontology:
Molecular function: glycosaminoglycan binding; heparin binding
Biological process: face morphogenesis; lung development
Cellular component: extracellular exosome; transport vesicle; extracellular region; ficolin-1-rich granule lumen; non-collagenous component of interstitial matrix; secretory granule lumen; extracellular matrix
Genetic constraint (gnomAD): Loss-of-function variants: 46 observed, 67.53 expected, observed/expected ratio (o/e) 0.68, 90% interval 0.54 to 0.87. The synonymous counts are far from expectation, so gnomAD's model fits this gene poorly and the ratio says little. Missense variants: 813 observed, 667.08 expected, observed/expected ratio (o/e) 1.22, 90% interval 1.15 to 1.29. Synonymous variants: 314 observed, 258.1 expected, observed/expected ratio (o/e) 1.22, 90% interval 1.11 to 1.34.
Homologues: Orthologues: chimpanzee CRISPLD2 (100% identical), macaque CRISPLD2 (98% identical), dog CRISPLD2 (88% identical), pig CRISPLD2 (86% identical), rat Crispld2 (80% identical), mouse Crispld2 (77% identical), rabbit CRISPLD2 (71% identical), tropical clawed frog crispld2 (70% identical), zebrafish crispld2 (61% identical), Drosophila melanogaster CG42564 (15% identical), Caenorhabditis elegans scl-10 (12% identical), Caenorhabditis elegans scl-5 (12% identical), and 41 more. Paralogues in human: CRISPLD1 (58% identical), PI15 (27% identical), R3HDML (24% identical), CLEC18A (21% identical), CLEC18B (21% identical), CLEC18C (21% identical), GLIPR1 (17% identical), CRISP3 (16% identical), CRISP2 (16% identical), GLIPR1L2 (15% identical), CRISP1 (15% identical), GLIPR1L1 (14% identical), and 1 more.
Diseases named in the same sentence as CRISPLD2 in open-access papers:
CRISPLD2 is named in the same sentence as 46 diseases in open-access papers, as found by Europe PMC text mining. Sharing a sentence is not in itself a finding about the gene and the disease. The quoted sentences say what the papers report.
asthma (5 papers, 2014 to 2023). "In addition to published evidence that CRISPLD2 may indirectly play a role in asthma, SNPs of this gene were associated with two asthma pharmacogenetic traits measured in asthma clinical trials." (PMID 24926665, 2014). "On the other hand, the CRISPLD2 gene, which was a DMP associated with both FEV1 and FVC in our study, was identified in a whole genome sequencing study in children with asthma as associated with FEV1/FVC." (PMID 35681244, 2022). "Together these results suggest a role for CRISPLD2 in modulating two asthma pharmacogenetic phenotypes." (PMID 24926665, 2014). "Our findings identified CRISPLD2 as a novel asthma pharmacogenetics candidate gene and provide transcriptome data to further explore the anti-inflammatory effects of GCs in the ASM." (PMID 24926665, 2014). "Further studies are required to understand the cell-specific expression of CRISPLD2 and its interactions with other asthma medications." (PMID 24926665, 2014). "In addition, CRISPLD2 also exhibits a broad range of anti-inflammatory properties in a series of inflammation-related diseases, including asthma and obesity." (PMID 37784129, 2023). "One of these genes, cysteine-rich secretory protein LCCL domain-containing, 2 (CRISPLD2; OMIM 612434), had single nucleotide polymorphisms (SNPs) that were nominally associated with two asthma drug response phenotypes (i.e., inhaled corticosteroid response and short-acting bronchodilator response)." (PMID 24926665, 2014).
cleft palate (4 papers, 2014 to 2022). Cleft palate is a fissure type embryopathy that affects the soft and hard palate to varying degrees. "CRISPLD2 has been reported in the context of non-syndromic cleft palate." (PMID 30961659, 2019). "The aim of this study was to evaluate single nucleotide polymorphisms (SNPs) in FOS, CASP8 and MMP2 and to determine their SNP-SNP interactions with CRISPLD2 variants in the risk of nonsyndromic cleft lip with or without cleft palate (NSCL±P) in the Brazilian population." (PMID 36661544, 2022). "The results suggest that the SNP rs4783099 in CRISPLD2 may contribute to an increased risk of NSCPO, and the SNP rs2237138 in JARID2 may hold a protective effect against non-syndromic cleft lip with or without cleft palate (NSCL ± P), in the Brazilian population." (PMID 31221977, 2019).
Sepsis (4 papers, 2013 to 2019). Sepsis is defined as life-threatening organ dysfunction caused by a dysregulated host response to infection. "The aim of this study was to examine the expression of CRISPLD2 in patients with sepsis and characterize the association of this protein with procalcitonin." (PMID 23799041, 2013). "Further studies are needed to clarify the potential association between CRISPLD2 expression and clinical outcomes to determine if it could be used as a novel sepsis biomarker." (PMID 23799041, 2013). "The protein product of CRISPLD2 is related to the innate immunity and it is one of the best-validated biomarkers in sepsis research." (PMID 31426444, 2019). "A subsequent study of CRISPLD2 found that its protein levels were decreased in blood serum of patients with septic shock compared to controls, patients with sepsis and patients with severe sepsis." (PMID 24926665, 2014). "Thereby, treatment with glucocorticoids not only reduces the production of pro-inflammatory cytokines in sepsis but also simultaneously to up-regulates CRISPLD2 protein secretion." (PMID 23799041, 2013). "The results obtained in the present study are consistent with those of previous work, showing that the CRISPLD2 serum levels were significantly different in sepsis patients compared with the healthy control group." (PMID 23799041, 2013). "The decreased expression of CRISPLD2 in septic shock and its association with PCT suggests CRISPLD2 as a potential biomarker in sepsis." (PMID 23799041, 2013). "Here, we conducted a prospective observational study, and found a considerable fluctuation in the CRISPLD2 concentrations of healthy populations compared with sepsis patients." (PMID 23799041, 2013). "In fact, a statistically significant association between CRISPLD2 and PCT levels in sepsis patients was demonstrated in the current study." (PMID 23799041, 2013). "Patients with sepsis exhibited higher CRISPLD2 levels than observed in healthy individuals (p = 0.001), but CRISPLD2 expression was not upregulated in patients with septic shock." (PMID 23799041, 2013). "The present study is the first to demonstrate the decreased expression of CRISPLD2 in septic shock and its association with PCT in sepsis." (PMID 23799041, 2013). "Patients with septic shock exhibited lower levels of CRISPLD2 than healthy, sepsis, and severe sepsis patients." (PMID 23799041, 2013). "The CRISPLD2 level was significantly higher in sepsis patients compared with that in the healthy population (p = 0.019) and significantly lower in patients with septic shock compared with that in healthy, sepsis, and severe sepsis (all p<0.001)." (PMID 23799041, 2013). "Patients with mild sepsis had slightly higher levels of CRISPLD2 than healthyindividuals." (PMID 23799041, 2013). "Whether low CRISPLD2 levels in sepsis patients reflects immunosuppression remains elusive." (PMID 23799041, 2013). "In addition, the CRISPLD2 levels in sepsis patients and healthy controls were similar, and, unlike PCT, the expression of CRISPLD2 did not change with the increasing severity of disease." (PMID 23799041, 2013). "However, age and gender did not impact the CRISPLD2 levels in the healthy controls and sepsis patient groups included in the present study." (PMID 23799041, 2013).
cleft lip (3 papers, 2019 to 2022). Congenital defect in the upper lip where the maxillary prominence fails to merge with the merged medial nasal prominences. "This locus showed evidence of paternal DNA methylation at two neighboring CpG dinucleotides located in the first intron of CRISPLD2, which encodes a cysteine-rich secretory protein and has been associated with non-syndromic cleft lip." (PMID 30961659, 2019).
endometriosis (3 papers, 2014 to 2019). The growth of functional endometrial tissue in anatomic sites outside the uterine body. "CRISPLD2 protein was significantly higher in the epithelium of ectopic lesions from women with endometriosis as compared to eutopic endometrium." (PMID 24955763, 2014). "We observed that the expression level of CRISPLD2 was significantly reduced in the endometrium from women with endometriosis." (PMID 24955763, 2014). "In summary, this study observed that dysregulation of CRISPLD2 in endometrium from women with endometriosis." (PMID 24955763, 2014). "Herein, we show that expression of CRISPLD2 is altered in the uterus of endometriosis patients, and CRISPLD2 is consistently expressed during pregnancy via P4-PR signaling." (PMID 24955763, 2014). "The increase of CRISPLD2 expression at the early secretory and dysregulation of its expression in endometriosis suggest progesterone (P4) regulation of CRISPLD2." (PMID 24955763, 2014). "Further confirming the comprehensive disruption of P4 signaling in endometriosis, HOXA10, IGFBP1, PLZF, MIG-6, and CRISPLD2, all PGR targets implicated in endometrial function based on mouse studies, have been shown to be dysregulated in endometriosis patients." (PMID 31387263, 2019). "Interestingly, the protein level of CRISPLD2 was significantly lower in the eutopic endometrium obtained during the secretory phase from women with endometriosis compared to cells from the control endometrium." (PMID 24955763, 2014). "Therefore, defining the specific role of CRISPLD2 would be requisite to further understand dysregulation of PR signaling pathways on etiology and infertility effect of endometriosis." (PMID 24955763, 2014). "Therefore, we compared the levels of CRISPLD2 protein in eutopic endometrium (n = 12) and ectopic lesions (n = 5) from women with endometriosis." (PMID 24955763, 2014). "As endometriosis is an E2-dependent disease, E2 regulation of CRISPLD2 was investigated." (PMID 24955763, 2014). "To determine if CRISPLD2 is dysregulated in endometriosis, we examined the expression of CRISPLD2 in endometrium from early secretory phase women with and without endometriosis using immunohistochemistry." (PMID 24955763, 2014). "Herein, we examined the expression of CRISPLD2 in endometrium from patients with and without endometriosis using immunohistochemistry." (PMID 24955763, 2014). "The expression of CRISPLD2 was significantly decreased in the endometrium of women with endometriosis in the early secretory phase compared to women without endometriosis." (PMID 24955763, 2014). "We next used immunohistochemical analysis to examine the cell-specific expression of CRISPLD2 in endometrium from proliferative phase (n = 6) and early (n = 7), mid (n = 8), and late (n = 5) secretory phase in women without endometriosis." (PMID 24955763, 2014). "In the present study, we investigated the expression level of CRISPLD2 in endometrium from patients with and without endometriosis." (PMID 24955763, 2014). "The expression levels of CRISPLD2 was scored by measuring expression intensity of early secretory phase women without endometriosis (n = 7) and eutopic secretory phase endometrium from women with endometriosis (n = 12)." (PMID 24955763, 2014). "Interestingly, CRISPLD2 is regulated by progesterone (P4) and its receptor (PGR) in the uterus, its expression is high during decidualization, constitutive during pregnancy and is dysregulated in patients with endometriosis." (PMID 29100496, 2017). "However, the function of CRISPLD2 has not been studied in endometrium and endometriosis." (PMID 24955763, 2014). "However, the function of CRISPLD2 has not been studied in endometriosis and uterine biology." (PMID 24955763, 2014).
orofacial cleft (3 papers, 2016 to 2022). A disorder of facial skeleton that is characterized by cleft lip and/or cleft palate that result in feeding, speech and hearing problems caused by failures during development. "Evidence has suggested that CRISPLD2, and genes in its pathway, may play important roles during craniofacial development, and the polymorphic variants in these genes may influence their function, contributing to nonsyndromic orofacial cleft susceptibility." (PMID 36661544, 2022). "As the SNPs rs1546124, rs8061351, rs2326398 and rs4783099 in CRISPLD2 were previously analyzed in this same case-control sample, we sought to verify whether SNP-SNP interactions among variants in CRISPLD2 and genes of its pathway could increase the prediction risk for nonsyndromic orofacial clefts." (PMID 36661544, 2022).
Alzheimer disease (2 papers, 2019 to 2024). A progressive, neurodegenerative disease characterized by loss of function and death of nerve cells in several areas of the brain leading to loss of cognitive function such as memory and language. "GSEA results showed that samples with deficiency of MTOR, CRISPLD2 or MORF4L1 showed consistent down-regulation in pathways of Alzheimer’s disease, Parkinson’s disease and Huntington’s disease." (PMID 31219803, 2019).
lung carcinoma (2 papers, 2014 to 2015). "The induction of CRISPLD2 by DEX that was observed in ASM did not occur in A549 pulmonary epithelial cells derived from a lung carcinoma tissue, as analogous treatment of A549 cells with DEX caused a decrease of CRISPLD2 mRNA." (PMID 24926665, 2014). "The results showed that four genes (GATA6, CRISPLD2, CFTR2 and CLPTM1L) have been proven to be involved in lung cancer." (PMID 26183581, 2015).
COVID-19 (1 paper, 2023). A disease caused by infection with severe acute respiratory syndrome coronavirus 2. "Therefore, B4GALT5, CRISPLD2 and F5 may be potent targets for the treatment of COVID-19-associated IS." (PMID 37606960, 2023). "Characteristic biomarkers showed high diagnostic efficacy in distinguishing COVID-19-related IS from control samples, with an AUC of 0.984 (95% CI 0.950–1,000) for B4GALT5, 0.966 (95% CI 0.914–0.998) for CRISPLD2, and 0.991 (95% CI 0.966 to 1.000) for F5." (PMID 37606960, 2023). "We then analyzed the mRNA expression of 9 genes, and 3 genes (B4GALT5, CRISPLD2, F5) were found up-regulated in both COVID-19 and IS (p < 0.001)." (PMID 37606960, 2023). "Then we screened 3 hub genes (B4GALT5, CRISPLD2, F5) which were up-regulated in both COVID-19 and IS by multiple machine learning methods combined with the mRNA expression of genes." (PMID 37606960, 2023). "Finally, three genes associated with immunity (B4GALT5, CRISPLD2, F5) and two genes associated with ferroptosis (ACSL1, CREB5) were identified up-regulated in COVID-19-related IS." (PMID 37606960, 2023).
disc degeneration (1 paper, 2026). "CRISPLD2 knockdown in NPCs led to disrupted redox balance, elevated lipid peroxides, and excessive iron accumulation, promoting oxidative stress-induced ferroptosis and disc degeneration." (PMID 41514293, 2026).
gram-positive bacterial infections (1 paper, 2013). Infections caused by bacteria that retain the crystal violet stain (positive) when treated by the gram-staining method. "The data obtained in the present study showed that patients infected with gram-negative bacterial isolates showed a lower level of CRISPLD2 than those with gram-positive bacterial infections." (PMID 23799041, 2013).
lung disease (1 paper, 2016). "To begin to explore the potential role of CRISPLD2 in adult lung disease, we investigated CRISPLD2 expression in lung fibroblasts isolated from controls and from COPD patients." (PMID 27597766, 2016).
respiratory infections (1 paper, 2013). "Patients with abdominal infections had higher PCT and lower CRISPLD2 levels than patients with respiratory infections." (PMID 23799041, 2013).
Shock (1 paper, 2013). The state in which profound and widespread reduction of effective tissue perfusion leads first to reversible, and then if prolonged, to irreversible cellular injury. "Patients with septic shock could consume more CRISPLD2 as a result of persistent bacterial antigen stimulation." (PMID 23799041, 2013).
Tetralogy of Fallot (1 paper, 2024). A congenital cardiac malformation comprising pulmonary stenosis, overriding aorta, ventricular septum defect, and right ventricular hypertrophy. "The associations between the Tetralogy of Fallot and the predicted gene CRISPLD2 (Cysteine Rich Secretory Protein LCCL Domain Containing 2) have also been validated by a systemic analysis for the pathogenesis of right ventricular (RV) failure." (PMID 39202774, 2024).
tumor (12 papers, 1987 to 2025). "In further exploration, it was found for the first time that SRGN can regulate CRISPLD2 expression through the YAP axis and positively promote tumor cell proliferation." (PMID 40384866, 2025).
cancer (6 papers, 2009 to 2022). A tumor composed of atypical neoplastic, often pleomorphic cells that invade other tissues. "The cells were then clustered into 17 clusters, with 11 cell types: macrophages, undefined cells, endothelial cells, mast cells, cancer stem cells, CRISPLD2+ cells, fibroblasts, myofibroblasts, smooth muscle cells, T cells, and natural killer (NK) cells." (PMID 36440052, 2022). "Clusters 1, 8, 10, 12, and 13 were classified as macrophages (11%), CRISPLD2+ cells (6%), cancer stem cells (4%), mast cells (2%), and endothelial cells (2%), respectively." (PMID 34153003, 2021). "There were 813, 506, 997, 563, 972, 870, 491, 530, 333, 799, and 726 highly expressed genes in the macrophages, undefined cells, endothelial cells, mast cells, cancer stem cells, CRISPLD2+ cells, fibroblasts, myofibroblasts, smooth muscle cells, T cells, and NK cells, respectively." (PMID 36440052, 2022). "We found 17 cell clusters that could be divided into eight cell populations based on marker genes, as follows: including fibroblast/smooth muscle cell, T cell/NK cell, macrophage, CRISPLD2+ cell, cancer stem cell, mast cell, endothelial cell, and undefined." (PMID 34153003, 2021). "We found that silencing of CRISPLD2 impacted transcriptomic changes related to multiple cell functions including hormone stimulation response, apoptosis, focal adhesion, chemokine signaling pathway, cancer, VEGF signaling, cell development, and differentiation in human lung fibroblasts." (PMID 27597766, 2016). "Unsupervised principal component analysis with the main cancer invasiveness-enriched genes (ASPN, GLT8D2, OLFML2B, CRISPLD2, ADAM12, POSTN, and PRRX1) allowed for the discrimination of subgroups of BMAL1-dependent CRC patients (p = 9.9 × 10−4)." (PMID 34065633, 2021).